INS (insulin)
Diseases named in the same sentence as INS in open-access papers (continued):
Sharing a sentence is not in itself a finding about the gene and the disease.
type 1 diabetes (continued). "Type I diabetes (T1D) results from chronic autoimmune destruction of insulin-producing β-cells mediated by self-reactive T-cells." (PMID 35784300, 2022). "Recently, several groups have demonstrated that unmethylated insulin (INS)-DNA is correlated to β-cell death in type 1 diabetes patients and during clinical islet isolation and subsequent transplantation." (PMID 35462792, 2022). "The diabetic rats in this study were deprived of treatment such as insulin replacement as we aimed to assess the effects of type 1 diabetes on bone healing." (PMID 36060973, 2022). "An insulin log and insulin bolus calculator was a feature that was either frequently used or named as a desired feature by people with type 1 diabetes." (PMID 35614419, 2022). "Meanwhile, GLUT inhibitor-conjugated insulin is being explored to mitigate the hypoglycemia side effect of insulin therapy in type 1 diabetes." (PMID 35552392, 2022). "The results also suggest that islet β-cell apoptosis and islet β-cell transdifferentiation mediate the insufficient secretion of INS in the development of alloxan-induced type 1 diabetes." (PMID 36467676, 2022). "Type 1 diabetes (T1D) is an autoimmune T-cell-mediated disease against pancreatic β-cells, which leads to the insufficient production of insulin and overt hyperglycemia." (PMID 35280980, 2022). "The partial remission (PR) phase, a period experienced by most patients with type 1 diabetes (T1D) soon after diagnosis, is characterized by low insulin requirements and improved glycemic control." (PMID 35280980, 2022). "CAR T cell therapy is also being used to treat type 1 diabetes, an autoimmune disease where multiple types of immune cells are involved in the destruction of insulin-producing beta cells." (PMID 35884798, 2022). "Insulin is usually obtained through subcutaneous injections, but today with technological development, insulin pumps help patients with type 1 diabetes manage their insulin administration." (PMID 36384715, 2022). "The current state of knowledge on the pathogenesis of type 1 diabetes proposes that insulin-producing β cells become altered and destroyed as a result of an autoimmune-mediated attack." (PMID 36250460, 2022). "Type 1 diabetes is one of the most common childhood diseases which requires lifelong insulin treatment." (PMID 35492685, 2022). "Transplantation of pancreatic islets is a promising alternative for exogenous insulin in patients with type 1 diabetes mellitus (T1DM)." (PMID 35838041, 2022). "Type 1 diabetes (T1D) is a chronic autoimmune disease destroying insulin-producing beta cells within the pancreatic islets, a result of tissue inflammation to specific autoantigens." (PMID 36389721, 2022). "Type I diabetes is characterized by insufficient insulin production or the inability of the pancreas to produce insulin." (PMID 36176638, 2022). "We believe this is the first report of insulin edema in an individual with type 1 diabetes occurring after transitioning to a hybrid closed-loop system." (PMID 36180933, 2022). "Insulin is the most effective drug in lowering glycemia, and for patients with type 1 diabetes (T2D), it is a life-saving treatment." (PMID 35324747, 2022). "This individualized user choice in method of insulin delivery for management of type 1 diabetes, brings into question both the appropriateness and the utility of randomized control trials (RCT), in the setting of these systems." (PMID 35951597, 2022). "Insulin is the most effective glycemic-lowering drug, and for people suffering from type 1 diabetes it is a life-saving drug." (PMID 35324747, 2022). "Type 1 diabetes, which is most common in children and young adults, is an autoimmune disease, which leads to the destruction of the insulin-producing pancreatic beta cells in the islets of Langerhans, which results in interference in insulin secretion." (PMID 35890680, 2022).
type 1 diabetes (continued). "Higher insulin production was observed in an animal model of type 1 diabetes treated with a nanodrug carrying the miR-216a mimic, as compared to untreated controls." (PMID 35711801, 2022). "Type 1 diabetes (T1D) arises through the immune-mediated destruction of insulin-producing pancreatic β-cells and results in dependence on life-long exogenous insulin replacement therapy." (PMID 35228584, 2022). "Type 1 diabetes (T1D) is a chronic autoimmune disease characterized by pancreatic beta cell destruction, leading to hyperglycemia and to a lifelong insulin-dependent state." (PMID 36743923, 2022). "Nearly 100 years ago the first type 1 diabetes (T1D) patient was treated with a “pancreatic extract,” which led to the discovery of insulin." (PMID 36055241, 2022). "The literature on dietary recommendations during pregnancy and breastfeeding mostly addresses women with type 1 diabetes but can also be applied to pregnant and breastfeeding women with type 2 diabetes and to women with insulin treated gestational diabetes." (PMID 36432552, 2022). "Are socioeconomic status disparities in insulin pump uptake in children with type 1 diabetes (T1D) different under the fully funded government program in Québec and the partially funded program in Manitoba?" (PMID 35507342, 2022). "Acarbose is an α-glucosidase inhibitor that can be used in combination with other oral hypoglycemic drugs or insulin to treat insulin-dependent or non-insulin-dependent diabetes." (PMID 36680115, 2022). "Treatment of pediatric patients newly diagnosed with type 1 diabetes with etanercept resulted in lower glycated hemoglobin and increased endogenous insulin production, suggesting the preservation of beta-cell function." (PMID 35563276, 2022). "Our data do not negate evidence indicating that beta cell abnormalities, such as incorrect insulin processing, HLA class I hyperexpression and irregular expression of immune genes contribute to the pathogenesis of type 1 diabetes." (PMID 35501400, 2022). "Data from 3C Study demonstrated that only a minority of patients with type 1 diabetes in China utilize insulin pump therapy." (PMID 35757419, 2022). "Regarding the significant effects of T. polium on β-cell regeneration and insulin secretion in animal models of type 1 diabetes, Tabatabaie and Yazdanparast (2017) ▶ investigated the molecular mechanism involved in the β-cell regeneration." (PMID 36186937, 2022). "Type 1 diabetes requires treatment with insulin injections and monitoring glucose levels in affected individuals." (PMID 35055576, 2022). "Recent advances in protein analytical technologies have expanded the list of neoantigens in type 1 diabetes, especially those derived from (pro) insulin." (PMID 35453564, 2022). "More than 100 years after the discovery of insulin, individuals with type 1 diabetes (T1D) still lack access to a treatment that halts disease progression and protects functional beta cells to prevent serious complications and early death." (PMID 35665810, 2022). "Type I diabetes results from autoimmune destruction of beta-cells (pancreatic insulin-producing cells)." (PMID 36290725, 2022). "Type 1 diabetes (T1D) is an autoimmune condition that results in destruction of insulin-producing β cells in the pancreatic islets, thereby leaving affected patients dependent on exogenous insulin therapy." (PMID 35667687, 2022). "There are mounting case reports and small-scale studies describing the benefits of the ketogenic diet in patients with type 1 diabetes, particularly related to improvements in glycemic control and variability, and reduction in insulin requirements." (PMID 36676967, 2022). "Values tended to be higher in profiles with a greater proportion of participants with type 1 diabetes and the use of insulin (i.e. “High users” and “Diabetologist first” profiles), but this must be interpreted with caution given the magnitude of missing data." (PMID 35498410, 2022).
type 1 diabetes (continued). "The identification of advanced technological systems for continuous blood glucose monitoring and the presence of insulin pumps had a beneficial effect, especially on patients with type 1 diabetes." (PMID 36556420, 2022). "This study aimed to investigate the application of insulin pump therapy among patients with type 1 diabetes in China." (PMID 35757419, 2022). "Studies on patients with type 1 diabetes treated with multiple insulin injections showed that the use of an automatic bolus calculator was associated with reduced FOH." (PMID 35620854, 2022). "We excluded studies focusing mainly on oral antihyperglycemic medications, type 1 diabetes, persons with insulin pumps, and studies older than 20 years." (PMID 35634376, 2022). "Type I diabetes (T1D) is an autoimmune disorder in which the insulin-producing cells—the β cells—in the pancreas are destroyed." (PMID 35954275, 2022). "Until recently, most individuals with type 1 diabetes have used multiple dailyinjection (MDI) or insulin pump regimens." (PMID 33472409, 2022). "He had history of insulin-dependent diabetes and had neglected his insulin shots on the day prior to hospital admission due to progressive loss of consciousness." (PMID 35655196, 2022). "Over the past several decades, there have been major advancements in the field of glucose sensing and insulin delivery for the treatment of type I diabetes mellitus." (PMID 36072265, 2022). "Non-insulin-based treatments for type 1 diabetes include glucose-lowering drugs (e.g., Pramlintide, GLP1 receptor antagonists, sodium–glucose cotransporter-2 (SGLT2) inhibitors) and pancreas and islet transplantation." (PMID 36012526, 2022). "As the insulin supply for type 1 diabetic patients comes from exogenous infusion, the insulin secretion term is denoted by u1(t)VolI, where u1(t) (μU/min) denotes the insulin infusion rate and VolI denotes the insulin distribution volume." (PMID 36619543, 2022). "In persons with Type 1 diabetes, such interventions have been mainly based on providing more stable insulin regimens, in order to reduce fluctuations in blood glucose levels." (PMID 35546667, 2022). "Type 1 diabetes (T1D) is described as a disease with a large genetic component that involves an auto-immune attack on insulin producing pancreatic beta cells." (PMID 36614008, 2022). "Combined therapy with cholecalciferol and lansoprazole for six months was associated with smaller decline in residual β-cell function and lower insulin requirements in children with new-onset type 1 diabetes." (PMID 36449759, 2022). "Successful transdermal insulin delivery was reported for Type 1 diabetes by incorporating insulin while fabricating a hyaluronic acid-based MN." (PMID 35458358, 2022). "Exercising with type 1 diabetes adds further complexity, mostly around matching insulin to the recommended high carbohydrate intake, but also because of the way in which higher circulating insulin levels affect glucose utilisation and fat oxidation." (PMID 36425473, 2022). "If a person living with type 1 diabetes decides to engage in more physical activity, they must make simultaneous changes to carbohydrate intake, as well as adjusting insulin-to-carbohydrate ratios." (PMID 38875589, 2022). "Type 1 diabetes (T1D), an immune-related disease characterized by the destruction of insulin-producing cells, affects a young population." (PMID 36497026, 2022). "Oral verapamil lowers inflammatory markers and daily insulin needs in subjects with type 1 diabetes and helps preserve pancreatic beta cell function for at least two years." (PMID 35241690, 2022). "Type-1 diabetes (T1D) is a classic example of an autoimmune disease characterized by the dysregulation of immune cells leading to the destruction of insulin-producing cells of the pancreas." (PMID 35158821, 2022).
type 1 diabetes (continued). "Some patients with newly diagnosed type 1 diabetes (T1D) experience, after starting insulin treatment, a period of clinical and metabolic remission commonly known as the “honeymoon phase”." (PMID 35315990, 2022). "According to a previous report, the blood ucOC level in patients with type 1 diabetes is considered to be determined by the dose of exogenous insulin injection." (PMID 35216490, 2022). "Type 1 diabetes is a worldwide autoimmune disease characterized by chronic hyperglycemia due to the destruction of insulin-producing pancreatic beta cells." (PMID 36611907, 2022). "In the 100 years since the discovery of insulin, this goal has evolved to include personalised approaches to type 1 diabetes diagnosis, treatment, prevention and prediction." (PMID 35994083, 2022). "The insulin mimicking activity of Polypeptide-p can be considered as a plant based alternative of insulin in type 1 diabetic patients." (PMID 35282429, 2022). "Type 1 diabetes results from the destruction of pancreatic β-cells by an autoimmune reaction leading to the inability to synthesize the hormone insulin." (PMID 35216316, 2022). "For example, Fu and coworkers constructed a closed-loop insulin smart delivery system for type 1 diabetes treatment." (PMID 36151726, 2022). "Genome-wide linkage analysis revealed one major QTL with higher blood glucose levels and increased pancreatic insulin on chromosome 13 (Nidd13/NZO for non-insulin-dependent diabetes on chromosome 13, derived from NZO) introduced by NZO alleles." (PMID 35328627, 2022). "There have also been frequent reports of depressive symptoms in patients with type 1 diabetes despite continuous insulin treatment." (PMID 36552776, 2022). "Nowadays the use of intensified insulin therapy is the standard treatment in patients with type 1 diabetes from onset of the disease." (PMID 35757419, 2022). "SOINS DM is a new application with interactive visualization between type 1 diabetes, patients, and the doctor, which facilitates blood sugar monitoring, adjusting insulin doses, physical activity, and diet." (PMID 36556420, 2022). "Type 1 diabetes is usually referred to as insulin-dependent, since it results from the failure of the pancreatic cells to secrete insulin and its complications are managed by injections of exogenous insulin." (PMID 36297817, 2022). "The 1920s marked a new era for people living with type 1 diabetes, with insulin injections effectively preventing death from severe insulin deficiency." (PMID 35994083, 2022). "The autoimmune destruction of the host pancreatic β cells that produce insulin results in a chronic disease named Type 1 diabetes (T1D)." (PMID 36032110, 2022). "Insulin replacement therapy is believed to contribute most to weight gain in people with type 1 diabetes, but it can also be affected by their behaviour, lifestyle choices, psychosocial factors and fear of hypoglycaemia." (PMID 35784568, 2022). "A total of 53 patients (n=35, 66% with type 1 diabetes; n=44, 83% treated with insulin) were included in this analysis." (PMID 35323114, 2022). "Living with type 1 diabetes (T1D) requires lifelong self-management of regular insulin intake and blood glucose monitoring, while maintaining a generally healthy lifestyle." (PMID 36078596, 2022). "During the development of type 1 diabetes (T1D), pancreatic β-cells are selectively destroyed, eventually leading to dependence on exogenous insulin." (PMID 36703975, 2022). "Another possible application area for sorafenib is the honeymoon phase of type 1 diabetes, a remission period where insulin usage can be sharply reduced or even withdrawn during the treatment of type 1 diabetes." (PMID 35242127, 2022). "Despite do-it-yourself automated insulin delivery being an unapproved method of insulin delivery, an increasing number of people with type 1 diabetes (T1D) worldwide are choosing to use Loop, a do-it-yourself automated insulin delivery system." (PMID 36279156, 2022).
type 1 diabetes (continued). "Type 1 diabetes mellitus is an autoimmune disease that leads to the destruction of pancreatic β-cells that secret insulin." (PMID 36406399, 2022). "Because SGLT2 inhibitors have a different mechanism of action to other glucose-lowering agents, they can be used in combination with other agents including insulin and can often reduce the amount of insulin required in type 2 and type 1 diabetes." (PMID 35113333, 2022). "For this reason, the effectiveness of MNT on glycemic control and insulin dose of individuals with type 1 diabetes should be focused on overall lifestyle interventions, including physical activity." (PMID 35459205, 2022). "Descriptive research in type-I diabetes has revealed insulin Degludec destined protective having declined hypoglycemic rate and equivalent glycemic control toward insulin glargine (analog) with long-lasting activity." (PMID 35723344, 2022). "This is important for translational research applications of evolving dual-hormone (insulin + glucagon) closed-loop artificial pancreas algorithms and their usage in type 1 diabetes." (PMID 35590248, 2022). "Exogenous insulin replacement by injection or insulin pump is necessary for survival and there is no cure for type 1 diabetes." (PMID 35012530, 2022). "Insulin overdose is the most common suicide method among type 1 diabetes patients; it is less frequently used by type 2 diabetics." (PMID 35324747, 2022). "In this study, we present a snapshot of the real-life use of insulin pump among people with type 1 diabetes with a relatively large sample size that was recruited from primary, secondary and tertiary levels of health facilities." (PMID 35757419, 2022). "Although CAR Tregs were successful in the model for MS, a similar study of anti-insulin CAR Tregs in NOD mice was ineffective at reducing or preventing type 1 diabetes, potentially due to the multiple forms of insulin present in the body." (PMID 35884798, 2022). "Type 1 diabetes is an immune-mediated disease characterized by the impairment of insulin-producing pancreatic beta cells." (PMID 35242127, 2022). "Patients having type 1 diabetes suffer from decrements in the required insulin level as a result of eradication of beta cells." (PMID 36298123, 2022). "C-peptide testing in those with clinically diagnosed type 1 diabetes can lead to reclassification and insulin withdrawal." (PMID 35994083, 2022). "Type 1 diabetes (T1D) is a T-cell-mediated autoimmune disease characterized by the irreversible destruction of insulin-producing β-cells in pancreatic islets." (PMID 36451229, 2022). "This cohort study compares use of insulin pumps in children with type 1 diabetes in Québec, Canada, where full funding is available, with use in Manitoba, Canada, where funding is partial." (PMID 35507342, 2022). "On January 23, 1922, at Toronto General Hospital, they administered purified bovine insulin for the first time to Leonard Thompson, a 14-year-old boy with type 1 diabetes: the boy’s elevated blood sugar was lowered." (PMID 35921488, 2022). "Type 1 diabetes (T1D) is a chronic autoimmune disease resulting from the destruction of insulin‐producing β‐cells with strong genetic background and environmental triggers." (PMID 36169248, 2022). "In contrast, there are other diseases where therapeutic proteins need to be administrated on a time scale of minutes or a few hours (e.g., insulin in type I diabetes)." (PMID 34586617, 2022). "This is due to fact that streptozotocin (STZ) damages the pancreatic islet β-cells, and prevents insulin secretion, thus results in type-1 diabetes." (PMID 35305622, 2022). "In summary, this study shows that serum Mg2+ levels are negatively associated with glycaemic control and to inflammation (log10 hs-CRP), but this relationship is limited to people with type 1 diabetes who are probably insulin resistant." (PMID 35440685, 2022).